INS (insulin)
Diseases named in the same sentence as INS in open-access papers (continued):
Sharing a sentence is not in itself a finding about the gene and the disease.
diabetes (continued). "This joint document of the Italian Diabetes Society and the Italian Society of Nephrology reviews the natural history of diabetic kidney disease (DKD) in the light of the recent epidemiological literature and provides updated recommendations on anti-hyperglycemic treatment with non-insulin agents." (PMID 31576500, 2020). "Diabetes drug use status after TBIR treatment was as follows for 17 cases (with duplicate use): 8 cases had no prescription, 6 cases used α-glucosidase inhibitors, 3 cases used glucagon-like peptide-1 receptor agonists, 2 cases used insulin, and 2 cases used biguanide." (PMID 32337291, 2020). "During pre-diabetes and early diabetes, beta cells adapt in response to muscle, hepatic and adipose tissue insulin resistance by enhancing GSIS and their hyperfunction largely contributes to increased insulin output, which is supported by beta cell mass expansion." (PMID 33182622, 2020). "On admission, subjects with the highest tertile of CV of FPG had longer duration of diabetes, higher levels of HbA1c, FPG and fasting insulin level, postprandial plasma glucose, LDL cholesterol and peak values of troponin I, but lower postprandial insulin level than those with the lowest tertile." (PMID 32878604, 2020). "According to the Immunology of Diabetes Society (IDS), LADA diagnosis is based on three criteria: a minimal age of 30 years at diabetes onset, the presence of circulating islet autoantibodies and lack of insulin requirement for at least 6 months after diagnosis." (PMID 33292447, 2020). "This may not be true for patients with diabetes mellitus since VNS may induce changes in appetite, energy regulation as well hormones such as incretins and GLP-1 that are associated with insulin secretion and glucose regulation." (PMID 32471438, 2020). "In Nigeria, every child with diabetes is self pay and not under any insurance so many receive mixed insulin or free mix insulin regimen while a few are on basal bolus regimen that requires insulin administration for every meal with a long acting at night or morning." (PMID 32874425, 2020). "While the overall PRS did not impact on diabetes progression, a sub‐PRS that incorporated only diabetes risk variants linked with insulin resistance showed association with time to insulin prescription (HR 1.39 (95% CI 1.09‐1.77)) in the intensified intervention group." (PMID 32318630, 2020). "Post hoc comparison using Sidak test indicated that there were statistically significant higher FBG values among participants who were not taking both oral diabetes medication and insulin compared with those who taking insulin only (MD = 0.17, 95% CI: 0.02, 0.31)." (PMID 32802365, 2020). "Diabetes is a chronic disease related to a dysfunction of the pancreas that occurs when that organ does not produce the correct level of insulin or the body does not use the insulin properly." (PMID 32961757, 2020). "Additionally, literature depicted previous research that demonstrated the effects of antidiabetic drugs (for example, aminoguanidine and insulin) in order to control the negative effect of diabetes mellitus on bone around the implant in rats." (PMID 33322243, 2020). "However, despite the apparent need for more automation in diabetes therapy, only the HCL Medtronic MinimedTM 670G, as the world’s first insulin pump with adaptive basal insulin delivery, has become marketable thus far, and eligible for reimbursement in Germany in September 2019." (PMID 33332410, 2020). "This hypothesis is supported by findings in an experimental study design that reported an association between GAD65 antibodies and a decrease in maximal insulin secretory capacity in people without diabetes." (PMID 31713011, 2020). "There were no reports of symptomatic or biochemical hypoglycaemia in any of the studies, even though approximately 17% of the patients with diabetes were taking ≥ 2 noninsulin blood glucose-lowering medications and approximately 8% were using insulin or an insulin secretagogue." (PMID 32907617, 2020).
diabetes (continued). "Thus, some persons with diabetes were unable to travel with insulin due to lack of storage facilities and whereas others simply feared the injection pain." (PMID 33091039, 2020). "Type 2 diabetes mellitus can be treated with monotherapy or various therapeutic combinations including metformin, sulfonylureas, thiazolidinediones, dipeptidyl peptidase-4 inhibitors (DDP-4), glucagon like peptide-1 (GLP-1) agonists, sodium-glucose co-transporter-2 (SGLT-2) inhibitors, or insulin." (PMID 32033451, 2020). "Second, there was no data on glucose control or use of insulin on patients with diabetes, which could affect gestational weight gain." (PMID 33224106, 2020). "However, owing to uncontrollable vigorous foreign-body responsive, rare matching type and expensive cost, the long-term glycemic control of diabetes is still widely used by insulin not transplantation of islets." (PMID 32664978, 2020). "Although communication with mothers does not increase self-care in girls with diabetes, it may reduce their HbA1c levels through other variables such as reducing anxiety and improving insulin regulation." (PMID 32252831, 2020). "The application of IGF-1 could be considered when an extreme IR or insulin insensitivity exists, while recombinant human IGF-1 might be an alternative strategy to normalize the blood glucose level and prevent acute complications of diabetes." (PMID 33905470, 2020). "By using different murine models of diabetes (glucose-induced hyperglycemia mouse model; db/db mice and Akita mice) as well as β-cells isolated from pancreatic donors, they argue that mild UPR drives ATF6-induced proliferation of β-cells based on the insulin requirement." (PMID 33613449, 2020). "In addition, one CAR activator, scoparone, did showed anti-diabetes effect in db/db mice without elevation of insulin levels." (PMID 33396516, 2020). "Due to the SARS-CoV-2, the pancreatic damage and the resultant impairment in β-cell insulin secretion may worsen preexisting diabetes or determine the appearance of hyperglycemia in nondiabetes." (PMID 33062712, 2020). "PIR, in particular, is present in all patients diagnosed with T2D, regardless of whether insulin has been administered or not, and should be treated through proper diabetes management, education and counselling." (PMID 32257276, 2020). "Diabetes mellitus, commonly referred to as diabetes, is clinically characterized by hyperglycemia due to insulin insufficiency arising from a lack of insulin production or insulin insensitivity." (PMID 32210089, 2020). "A recent trial from UCSF on adult patients with diabetes that utilized GMP polyclonal Treg cells ranging from 5 million to 2.6 billion showed that Treg cell therapy is safe and that there was stable C peptide levels and insulin for 2 years after GMP Treg cell therapy." (PMID 33072105, 2020). "First, although a number of potential confounding factors, such as age, sex, diabetes duration, BMI, glycated hemoglobin, SBP, GFR, smoking, and insulin were controlled for in the multivariate regression analysis, other unrecognized confounding variables may exist." (PMID 32962704, 2020). "Treatment of diabetic subjects with some β-adrenoceptor blockers was shown to have beneficial effects; treatment of diabetic animals with propranolol (75 mg/kg/day) attenuated diabetes-induced cardiac dysfunction without any changes in plasma glucose or insulin levels." (PMID 32244448, 2020). "Notably, the simultaneous overexpression of TRα1 and the administration of T3 enhanced cell cycle progression and proliferation, leading to the reprogramming of pancreatic cells into insulin-producing cells, in both the rat β-cell line and in an animal model of STZ-induced diabetes." (PMID 33519447, 2020). "It is certainly tempting to think that women being managed with metformin might have less severe diabetes than those requiring insulin therapy, but the current databases do not provide such laboratory data in our population." (PMID 32887578, 2020).
diabetes (continued). "Insulin secretary dysfunction is reflected in impaired glucose tolerance, which precedes the development of diabetes mellitus, and in which β‐cells can no longer rapidly respond to changes in blood glucose concentration and adjust insulin secretion to compensate for systemic insulin resistance." (PMID 33102766, 2020). "Third, in clinical trial B no measurements were performed on anthropometric or surrogate metabolic parameter to assess insulin resistance other than BMI, lack of overt dyslipidemia and lack of diabetes to establish whether subjects were metabolically stable." (PMID 32272659, 2020). "Sixthly, insulin data was not available for all participants; despite this, we studied a subgroup of our population with measurements of insulin level and showed a signal for higher risk of CVD/CHD among those who converted from IR to diabetes." (PMID 32228577, 2020). "In individuals from the Jordan National Center for Diabetes, there was a higher probability of success in patients who had T2DM for seven or fewer years; with respect to the therapeutic profile, the ascending probability of success was as follows: both OAD and insulin; only insulin; only OAD." (PMID 32629460, 2020). "In the early stage of diabetes, B cells could overcome the lack of insulin action by increasing insulin secretion." (PMID 32596376, 2020). "A previous study showed lower expression of proteins regulating mitochondrial function in abdominal SAT of insulin-resistant compared with insulin-sensitive humans without diabetes, but these differences were less pronounced, when both groups were matched for BMI and percent body fat." (PMID 31838512, 2020). "However, during the researcher’s (WTT) interview with the diabetes MO in-charge, the individual demonstrated a lack of interest with the insulin PDA and was also in a hurry to end the interview session." (PMID 33378349, 2020). "Beta cell function, insulin sensitivity and glycaemic control were modelled from frequently sampled 75 g OGTTs (fsOGTTs) and mixed-meal tolerance tests (MMTTs) in participants without and with diabetes, respectively." (PMID 32002573, 2020). "Diabetes is a metabolic disorder that appears owing to a reduction of insulin and, if not treated in time, it could have severe repercussions on the nervous system, heart, kidneys, eyes, and skin." (PMID 32825791, 2020). "Mutations in the mitochondrial genome may also reduce the ability of mitochondria to generate ATP; the lack of ATP would inhibit the ability to transport insulin and glucose, which could play a role in the development of diabetes." (PMID 32457801, 2020). "Diabetes mellitus (DM) is a chronic condition that is due to a lack of insulin from the pancreas or an inadequate efficiency of insulin level leading to severe complications in many parts of the body and significantly increasing the risk of disability and premature death." (PMID 32140920, 2020). "In this paper, we have made a detailed study of effects of S. platensis on pancreatic insulin release, dipeptidyl peptidase IV (DPP-IV) inhibition and various gastrointestinal (GI) tract actions to elucidate the mechanism and therapeutic potential of S. platensis for improvement of diabetes control." (PMID 32517842, 2020). "Thus, the lack of response to insulin in diabetes during pregnancy and clinical implications of these immunological parameters deserves further investigations." (PMID 32626786, 2020). "Our patient has not manifested any changes in blood glucose, glucagon, or insulin levels, but he may develop later‐onset diabetes." (PMID 32277595, 2020). "Moreover, most patients in both groups reported the use of insulin to control diabetes, with 38 (67.8%) in the T2DM group without RA and 17 (85%) in the T2DM group with RA." (PMID 32130282, 2020).
diabetes (continued). "Drawing on observation and interview reflection notes, the current leadership appeared to be lacking in Clinic B and this might affect the insulin PDA implementation even though a diabetes team is present." (PMID 33378349, 2020). "Moreover, considering the phenomenon of “Burnt-Out Diabetes” after progression into ESRD, the use of insulin in dialysis cohort may represent a relative higher HbA1c or more fluctuated serum glycemic status." (PMID 33172034, 2020). "Also, following STZ induction of diabetes, the mice did not receive insulin to treat the hyperglycemia until the clamp procedure, which is unlike the optimal situation in humans with type 1 diabetes in which normoglycemia would be the goal." (PMID 33042003, 2020). "The effect of CPP extract on various genes such as Pdx-1, Ins-1, ngn-3, GLUT-4, and IRS-1 in insulin signaling pathway and Traf-4, Traf-6, and Mapk-8 in MAPK downstream JNK cascade was examined through qRT-PCR to access the core molecular mechanism involved in CPP-induced recovery of diabetes." (PMID 32256963, 2020). "Although medication is beneficial for T2DM and has been advocated as a core component for diabetes treatment, some patients continue to inject and administer oral insulin when blood sugar levels are not adequately controlled, leading to low blood sugar and serious complications." (PMID 33332396, 2020). "Diabetes is characterized by increased appetite (polyphagia) concomitant to decreased uptake and utilization of glucose by peripheral tissues; such effects are due to the lack of insulin or because the insulin pathway signaling is impaired." (PMID 33203103, 2020). "In the Botnia Study, GADA (vs no GADA) predicted non-insulin-requiring diabetes (HR 4.9), while in the Nord-Trøndelag Health Study (HUNT), even evanescent GADA predicted diabetes and these diabetes patients tended to be younger, with lower C-peptide and higher HbA1c." (PMID 31813006, 2020). "Furthermore, differences in the clinical implications of insulin use among patients with and without diabetes have not been thoroughly examined, since insulin use is typically driven by the blood glucose level without direct regard for diabetic status." (PMID 33118731, 2020). "Most study participants defined diabetes as the presence of high blood sugar levels in the body (78.7%), but nearly half of the study participants did not know DM as a condition of insufficient insulin production." (PMID 32214398, 2020). "Additionally, terms related to diabetes (i.e., glycemic control, glucose, insulin, blood sugar, etc.)or diabetes comorbidities were not searched." (PMID 32341338, 2020). "On the contrary, patients with long‐standing diabetes require polytherapy (oral anti‐diabetic drugs (OADs) and/or insulin), which may not provide an opportunity to explore the sole effect of metformin on mitophagy in these patients." (PMID 31975558, 2020). "Whether or not glucose and insulin disturbances observed during diabetes enhance arrhythmogenicity of the atria, potentially leading to AF, is not well-known." (PMID 32903422, 2020). "In the present study, correlations between ucOC and indices of insulin secretion and sensitivity were analyzed in normal glucose tolerance (NGT), impaired glucose metabolism (IGM), and diabetes mellitus (DM) groups." (PMID 32821293, 2020). "In an animal study, sufentanil postconditioning significantly diminished the size of myocardial infarct by 46% in nondiabetic rats (P<0.001), but diabetes prevented the cardioprotective effect of sufentanil, which was restored during long-term insulin treatment." (PMID 32461758, 2019). "Diabetes is a chronic metabolic disease due either to a lack of insulin secretion or a reduced insulin sensitivity, with high blood sugar levels being the main characteristic, and is often associated with fat, protein and electrolyte metabolic disorders and acid-base imbalance." (PMID 31307454, 2019).
diabetes (continued). "Different names such as “J type diabetes”,phasic insulin dependent diabetes mellitus (PIDDM) and ketosis resistantdiabetes have been used in different studies for phenotypes similar to PDPD withan additional criterion of high daily insulin requirement which may denoteinsulin resistance." (PMID 31673335, 2019). "The complexity of the knockout phenotype, with better preservation of insulin sensitivity and yet higher peak glucose levels following glucose challenge, led us to question whether PPP1R15A antagonism would be beneficial or detrimental in models of diabetes." (PMID 30814564, 2019). "Hence, type 1 diabetes patients need daily insulin injection to regulate the glycometabolic system, but few patients suffer from brittle diabetes and do not have an appropriate quality of life." (PMID 31406275, 2019). "The apparent categorical difference between the two major types of diabetes has been challenged, with the realisation that some adult-onset type 1 diabetes cases may not initially need insulin treatment and can have similar C-peptide levels as in type 2 cases." (PMID 31558146, 2019). "In anotherstudy, subgroups of KPD were defined using different names, such as KPDM-insulinin which diabetes could be controlled after discontinuing insulin and usingalternative treatments and KPDM+insulin characterized by insulin requirement forlife in order to manage hyperglycaemia." (PMID 31673335, 2019). "Critically, this translated into significant reductions in exendin-4-induced insulin secretion, indicating that GLP-1R palmitoylation may play an important role in glucose homeostasis or responses to pharmacological GLP-1R agonists in diabetes." (PMID 31430273, 2019). "Data on weight, insulin, GLP-1 RA and SGLT-2i use were collected retrospectively (12 years) and prospectively (8 years) from patients included in the DIAbetes and LifEstyle Cohort Twente-1 (DIALECT-1, n = 450, age 63 ± 9 years, 58% men, diabetes duration years)." (PMID 31216324, 2019). "DM is linked with pancreas and inslin secretion, it may affect when the pancreas does not produce (type 1 diabetes) sufficient amount of insulin (a hormone, which regulates the blood sugar level) or when the body does not utilize (type 2 diabetes) enough amount of insulin produced by the pancreas." (PMID 31871947, 2019). "He poorly engaged with diabetes services and had not attended his diabetes clinic appointments for two years prior to presentation, solely attending his general practitioner when repeat insulin prescriptions were required." (PMID 31266485, 2019). "The use of loop diuretics was much more frequent in insulin‐treated patients (80%) than in those with diabetes not on insulin (66%) and especially compared to those without diabetes (56%), as was the use of lipid lowering agents (65%, 50%, and 35% of each group, respectively)." (PMID 31271255, 2019). "To develop personalized psychological support for T1D patients at Unicamp Diabetes Clinic accordingly, we propose to investigate the emotional burden of T1D in different age groups, patients who received different insulin regimens (IRs) and patients with and without chronic complications." (PMID 31890038, 2019). "Diabetes mellitus (DM) is a systemic and chronic metabolic disorder leading to chronic hyperglycemia that is characterized by disturbances by carbohydrate, protein and fat metabolism due to partial or complete lack of insulin and/or insulin resistance." (PMID 31777484, 2019). "While T1DM is characterized by its acute onset and life-long dependence on exogenous insulin, LADA is a slowly progressive form of T1DM, characterized by adult onset, presence of circulating islet autoantibodies, and insulin independence at least within 6 months after diagnosis of diabetes." (PMID 31632345, 2019).